HLF (HLF transcription factor, PAR bZIP family member)
Diseases named in the same sentence as HLF in open-access papers (continued):
Sharing a sentence is not in itself a finding about the gene and the disease.
cancer (continued). "Therefore, analyzing the expression profile of the HLF gene along with other markers could be utilized as a useful predictive marker for the evaluation of cancer treatment efficacy." (PMID 38711550, 2024). "Indeed, especially at high concentrations, both hLf and bLf and even more their derived peptides have been found to promote cytotoxicity and cell death for both prokaryotic and eukaryotic pathogens, as well as for cancer cells." (PMID 32183434, 2020). "No oncofetal genes were significantly upregulated in PGCC's early progeny, whereas 19 genes were suppressed (including HLF and KRT19), compared with initial cancer cells." (PMID 41287033, 2025). "The results suggested that the expression levels of HLF, CHRDL1, and SELENBP1 in cancer tissues were significantly lower than those in normal tissues (p < 0.05)." (PMID 35205284, 2022). "This shows that genes containing conserved RELA, STATI, IRFI, NF-kappaB, PEND, HLF, REL, CEBPA, DI_2, and NFKB1 binding sites are indeed over-represented in cancer-related DEGs and this over-representation can be recuperated computationally." (PMID 29593668, 2018). "Deregulations of miR-21 and miR-130b, as well as deregulation of GPD1L, HLF, HPGD and MGLL have been reported either in HNOC or other cancer types, and these MRMs represent significant functional relevance in OTSCC." (PMID 27561985, 2016). "Mechanistically, HLF regulates LPXN expression, modulating the integration of collagen’s mechanical cues with the actin cytoskeleton through Paxillin, thereby suppressing cancer cell migration and lung metastasis." (PMID 40473600, 2025). "Western blot analysis confirmed significantly lower expression levels of HLF, NUPR1, and HPCAL1 in NCI-H1975 and A549 cancer cells (p < 0.05), suggesting these genes may be involved in the development of LUAD." (PMID 40421217, 2025). "At odds with these findings, a negative correlation between endogenous hLf expression and cancer incidence was demonstrated in different cancer cell lines, all showing a marked down-regulation of hLf transcript." (PMID 32183434, 2020). "Moreover, hLf-treated mice showed an increase of serum INF-γ, IL-2, and TNF-α, along with a down-regulation of serum IL-4 and cancer tissue VEGF." (PMID 32183434, 2020). "Furthermore, we determined the potential molecular mechanisms through which HLF may mediate immune infiltration, cell apoptosis, EMT, and cell cycle pathways and participle in cancer progression and drug resistance." (PMID 38711550, 2024). "In addition, HLF and ARID5B were identified as TFs of Tregs in precancer stages (e.g., N_HPV, AAH, NEOLP, EOLP), while regulons such as FOXO1 and STAT5B were specifically detected in cancers (e.g., IDC, AIS, MIAC, IAC and PDAC)." (PMID 38645221, 2024).
infection (11 papers, 2011 to 2025). The state of being infected such as from the introduction of a foreign agent such as serum, vaccine, antigenic substance or organism. "hLF is likely to act as a negative regulator by suppressing the acute response to estrogen or infection through a sharp increase in protein expression." (PMID 40286136, 2025). "These cells enter the site of infection and differentiate into macrophages in an hLF-rich microenvironment." (PMID 37868991, 2023). "As a first step, we investigated the structural features whereby hLF mediates HAdV-C5 infection of human respiratory A549 cells." (PMID 32376620, 2020). "HAdV-C5, HAdV-B35, and HAdV-A31 hexons all show very different affinities for hLF/hLfcin, which correspond to their different abilities to utilize hLfcin for infection." (PMID 32376620, 2020). "In vivo, hLF and hLfcin are constantly present in the respiratory mucosa, and thus we can expect the effect of hLF/hLfcin-mediated infection to increase over time as the infection progresses." (PMID 32376620, 2020). "Human Lf (hLf) is a cationic molecule of the innate immunity, constitutively synthesized by exocrine glands and, following the induction, by neutrophils in infection and inflammation sites." (PMID 32344579, 2020). "Since 1994, an effective antiviral activity of both hLf and bLf during the early stage of infection of enveloped and naked viruses was demonstrated." (PMID 28914813, 2017). "Even if the hLf concentration increases in infection and inflammation processes, in sputum of CF patients, free iron concentrations remain higher than in normal subjects." (PMID 28914813, 2017). "Preabsorption of cultured vertebrate cells with hLF strongly inhibited infection of cells by HS-adapted Alphaviruses, such as Semliki Forest virus (SFV), but not the non-adapted SINV strain TR339." (PMID 25533661, 2014). "hLf as well as bLf, independently of iron-saturation or the presence of sialic acid, inhibited infection and replication of HSV-1 in human embryo lung cells." (PMID 21847071, 2011). "Results obtained demonstrated that lactoferrin was able to prevent in vitro infection only by heparin sulfate-adapted viral strains suggesting that hLf inhibited infection of heparan sulfate-adapted alphavirus by interfering with virus-receptor interaction." (PMID 21847071, 2011). "Therefore, at the sites of infection and inflammation, the amount of secreted neurophilic hLF increases several-fold." (PMID 40286136, 2025). "Considering the high amount of hLF synthesized by granulocytes at the site of infection, hLF-induced upregulation of transcripts relevant to phagocytosis, proinflammatory cytokine signaling, and cell migration may aid pathogen clearance." (PMID 37868991, 2023). "Furthermore, we show that hLfcin peptides enhance infection more efficiently than the full-length protein, despite a lower affinity of the hLfcin1-49-hexon interaction than that of the hLF-hexon interaction." (PMID 32376620, 2020). "Utilization of hLF/hLfcin by species C HAdVs could also account for the frequent and persistent infections of species C HAdVs in tonsil T lymphocytes in young children." (PMID 32376620, 2020). "In this study, we investigated the molecular mechanisms behind hLF-dependent infection." (PMID 32376620, 2020). "We have previously shown that hLF facilitates HAdV-C5 infection of CAR-negative T cells." (PMID 32376620, 2020). "Next, we wanted to investigate if the antimicrobial peptide of hLF, hLfcin, could mediate HAdV-C5 infection on its own." (PMID 32376620, 2020). "Thus, hLf administered by peroral route provides therapeutic action against infection and inflammation in remote sites such as the urinary tract." (PMID 28257033, 2017).
infection (continued). "Data from studies of infection with L. monocytogenes in mice indicate that treatment with hLf displayed significant effects on one main organ target of this pathogen in regards to bacterial colonization, necrosis, and mRNA expression of pro-inflammatory cytokines TNFα, IL-1β and IFNγ." (PMID 28257033, 2017). "Similarly, Waarts and colleagues demonstrated that hLF strongly inhibited infection of vertebrate cells (BHK-21) by HSPG-adapted Alphaviruses (70% reduction in virus plaques for TRSB, and 90% reduction for SFV), but no reduction for non-adapted TR339." (PMID 25533661, 2014). "Thus, as ions are pumped in and out of the cells, the local ionic strength is altered to a degree that may, at times, be beneficial for the hLF-mediated infection of the epithelium." (PMID 38323814, 2024). "In this study, we provide structural and biochemical data for the interaction between hLF and the HAdV-C5 hexon, which fills an important gap in our understanding of how HAdVs engage hLF for a CAR-independent infection of epithelial cells." (PMID 38323814, 2024). "In addition to coagulation factors, species C HAdVs have been shown to use hLF and its proteolytic cleavage product lactoferricin (Lfcin), a highly positively charged, 49 amino acid peptide with antimicrobial activity, for enhanced infection of epithelial cells." (PMID 38323814, 2024). "Collectively, these data suggest that the major anchoring point for hLF/hLfcin1-49 is located within HVR-1 of the hexon, where the relative acidity of HVR-1 determines the ability to use Lfcin for infection." (PMID 32376620, 2020). "Differently, bLf and hLf were found both potent inhibitors of HPV-5 and -16 infections [ex115ora 116]." (PMID 21847071, 2011). "Assuming that a similar mechanism is used by hLfcin, we aligned hexon amino acid sequences of HAdVs known to use hLF for enhanced infection (such as HAdV-C5), with those of HAdVs expected not to use hLF (such as HAdV-A31 and HAdV-B35)." (PMID 32376620, 2020). "However, in mucosa, the three species of hLF (hLfcin, hLF, and hLF without hLfcin) potentially coexist in a complex equilibrium that probably shifts during infection/inflammation." (PMID 32376620, 2020).
bacterial infection (1 paper, 2024). "Lactococcus casei (La. casei) was designed to express human lactoferrin (hLF) as an antibacterial agent which showed significant clearance of E. coli by enhancement in phagocytosis and iron depletion in murine model with bacterial infection." (PMID 38495751, 2024).
hematological malignancies (1 paper, 2025). "Notably, HLF functions as an oncogenic chimeric transcription factor constituting central drivers in hematological malignancies yet acts as a metastasis-suppressive transcription factor constituting central suppressors in solid tumors." (PMID 40473600, 2025).
neurodegenerative disease (1 paper, 2025). A disorder of the central nervous system characterized by gradual and progressive loss of neural tissue and neurologic function. "To date, bLf is considered more reliable than hLf for therapeutic applications in neurodegenerative diseases due to its higher stability, bioavailability, and iron-binding properties." (PMID 41373469, 2025).
HLF also shares sentences with these, for which no sentence is quoted: B-cell acute lymphoblastic leukemia (4 papers); acute leukemia (2); liver cancer (2); sarcoma (2); acute myeloid leukemia (1); behavior disorders (1); bladder carcinoma (1); Burkitt lymphoma (1); B‐cell precursor acute lymphoblastic leukemia (1); Cirrhosis (1); endometrial cancer (1); gastritis (1); glioblastoma (1); graft versus host disease (1); HCMV infection (1); interstitial lung disease (1); lymphopenia (1); melanoma (1); osteosarcoma (1); poliovirus infection (1); rectal cancer (1); renal carcinoma (1); skin cancer (1); skin cutaneous melanoma (1); skin squamous cell carcinoma (1); steatosis (1); T-Cell Lymphoma (1); T-cell precursor acute lymphoblastic leukemia (1); vaginal infections (1).